TLR3 (toll like receptor 3)
Diseases named in the same sentence as TLR3 in open-access papers (continued):
Sharing a sentence is not in itself a finding about the gene and the disease.
tumor (continued). "In sum, the results presented herein demonstrate that through the recognition by TLR3, EBERs can induce tumor cells to produce cytokines in vivo that potentially recruit and activate macrophages, leading to a protumorigenic microenvironment for solid tumor growth." (PMID 26172457, 2015). "Here, we speculate that enhanced tumor cell death in the presence of both drugs releases more free RNA, which in-turn enhances TLR3 triggering and increases immune activation." (PMID 26287667, 2015). "Decreased TLR3 expression was related to tumor cell proliferation, upregulated angiogenesis, and inhibition of apoptosis, which may be associated with tumor progression and poor prognosis of patients with HCC." (PMID 25884709, 2015). "Here we assessed whether combining the TLR3 agonist: lysine-stabilized polyinosinic-polycytidylic-acid (poly-ICLC) with Sorafenib could enhance tumor control in HCC." (PMID 26287667, 2015). "For example, administration of the TLR3 agonist polyinosinic-polycytidylic acid (poly-IC) together with an antibody against programmed death-ligand 1 (PD-L1) leads to significant improvement in tumor control in mouse models of several different cancers." (PMID 26287667, 2015). "To investigate whether TLR3 activation promotes induction of breast CSCs in vivo, we treated tumor-bearing mice with poly(I:C), and then analyzed the excised tumors for CSC-associated properties." (PMID 25257174, 2015). "In particular, since elevated TLR3 expression was also highly expressed in other cancer patients and reversely correlated with poor prognosis, it is possible that inhibition of tumor TLR3 pathways may facilitate cancer treatment." (PMID 25257174, 2015). "Notably, all the B16 tumors in WT group grew about 2 times faster than that in TLR3−/− mice, which indicates TLR3 is favorable for tumor growth in vivo." (PMID 26172457, 2015). "Importantly, in consistence with the in vitro studies, MDA5 and TLR3 expression in tumor tissues also showed a synergistic effect on NB patient survival." (PMID 26208481, 2015). "Indeed, Ampligen, composed of poly (I:C) (a TLR3 agonist), has been shown to inhibit a variety of tumor growth in early clinical trials." (PMID 25101092, 2014). "Activation of dendritic cells by TLR3 agonists not only contributes to induction of innate and adaptive immune responses against microbial pathogens, but also favors NK cell activation and killing of tumor cells by stimulating anti-tumor CD8+ T cells." (PMID 26344622, 2014). "Condition medium from poly (I:C)-treated LNCap and DU145 cells recruited leukocyte subpopulation, indicating that TLR3 activation might influence early immune responses in tumor microenvironment." (PMID 25101092, 2014). "However, using an in vitro cytotoxicity assay, we observed a significant decrease in killing of FV-derived tumor cells (FBL-3) by NK cells isolated from FV-infected TLR3−/− mice in contrast to NK cells from wild type mice." (PMID 25539593, 2014). "Also, stimulation of human GAMs by the TLR3 agonist poly(I:C) results in tumor cell death and inhibition of tumor cell growth and invasion." (PMID 23864876, 2013). "In this view, the activation of TLR3 on the membrane of cancer cells could act as a trigger for the immune response against cancer and, by inducing both tumour cell death and anticancer immune stimulation, could synergize for optimal immunochemotherapy in PCa." (PMID 23551576, 2013). "Interestingly, although conflicting reports have been published concerning the pro- or anti-tumoural role of several TLRs, literature data agree on an anti-tumour role for TLR3 in various cancers." (PMID 23551576, 2013). "For example, in a randomized clinical trial for the efficacy of poly (A : U) dsRNA, therapeutic effect was mediated through TLR3 expressed on tumor cells, and could therefore represent an effective targeted treatment in patients with TLR3-positive cancers." (PMID 22295250, 2012).
tumor (continued). "Beside the EBER RNAs, there are other potential ligands of TLR3 in tumor tissues." (PMID 23198710, 2012). "Both TLR3 and TLR4 expressions were significantly and positively associates with tumor size." (PMID 21129170, 2010). "A significant association between TLR3 or TLR9 expression score and tumor stage was also found." (PMID 21129170, 2010). "Indeed, we have recently confirmed that Ly6AE-upregulation on CD8 T cells occurs in a strictly IFN-α/β-dependent manner after AB1-HA tumor treatment with the TLR3 and TLR7 agonists poly-I:C and imiquimod." (PMID 19746156, 2009). "Many of these signaling elements are also involved in tumor growth and apoptosis, implying that TLR3 expressed in tumor cells may also affect tumor viability." (PMID 18199340, 2008). "We found that all these tumor cell lines expressed TLR3 mRNA." (PMID 18199340, 2008). "Our study demonstrated the proapoptotic activity of TLR3 expressed by various tumor cells, which may open a new range of clinical applications for TLR3 agonists as an adjuvant of certain cancer chemotherapy." (PMID 18199340, 2008). "Expression changes of TLR3 and TLR4 in different cancers were basically consistent, which was closely related to multiple roles of TLR3 and TLR4 as pattern recognition receptors in driving tumor-associated inflammatory cascades, activating immunity and even regulating metabolic reprogramming." (PMID 40535567, 2025). "Since TLR3 agonists, such as dsRNA fragments, may be consistently present in the HNSCC tumor microenvironment and necrotic fluids, these endogenous DAMPs may create a positive feedback loop by further activating TLR3, potentially driving a pro-tumorigenic effect, as we have previously reported." (PMID 40647457, 2025). "In summary, S100A11 knockdown and TLR3 overexpression promoted anoikis and diminished the malignancy of tumor cells, indicating that S100A11 expression might be positively correlated with anoikis resistance and a poor prognosis, whereas TLR3 expression was negatively correlated." (PMID 39981252, 2025). "This duality underscores the need for careful consideration and monitoring of TLR3 agonists in anti-tumor therapies, as they may shift the inflammatory balance to either drive tumor regression or inadvertently promote tumorigenesis depending on the context and duration of treatment." (PMID 39988665, 2025). "Moreover, it has been shown that TLR3 stimulation can switch macrophages from an anti- to a pro- inflammatory phenotype/profile, leading to tumour regression, indicating that signalling through TLR3 can regulate TAM phenotype and possibly function and warrants further investigation." (PMID 40385641, 2025). "Therefore, by focusing on TLR3 signaling in DCs, tumor-specific cytotoxic T cells can be produced." (PMID 40727443, 2025). "We have previously shown that TLR3 may play a role in tumor metastasis." (PMID 40647457, 2025). "In addition, TLR3 agonists can activate tumor-specific immune responses in mice and patients." (PMID 39981252, 2025). "Moreover, they suggest the TLR3/TICAM-1 may contribute to previously reported CXCL10-mediated recruitment of CXCR3-positive lymphocytes to the tumor microenvironment." (PMID 40029556, 2025). "Additionally, some studies found curcumin could modulate inflammatory responses and tumor microenvironment by decreasing the expression of TLR3." (PMID 40535567, 2025). "Poly(I:C), recognized by TLR3, could promote the maturation and activation of dendritic cells, and enhance the activity of cytotoxic T cells, etc., thereby promoting the immune system to enhance the ability to recognize and attack tumor cells." (PMID 38671318, 2024). "Importantly, exosomal tumor RNAs are found to activate the Toll-like receptor 3 (TLR3) of the alveolar epithelium to activate chemokines (CXCL1, CXCL2, CXCL5, and CXCL12) that are key for neutrophil recruitment and pre-metastatic niche creation inside the lung." (PMID 38397421, 2024).
tumor (continued). "Thus the inhibition of the TLR3-mediated M2 macrophages phenotype shift towards the M1 could increase M2 cells fraction and consequently reduce the immune activation against the tumor." (PMID 38776331, 2024). "Therefore, whether the activation of TLR3 can promote anti-tumor M1-phenotype macrophages, still remains an open question particularly in smoking context." (PMID 38776331, 2024). "However, Zheng’s work suggests that TLR-3 may have both pro- and anti-tumor effects, depending on the context of the tumor microenvironment." (PMID 39273213, 2024). "In addition to its well-characterized role in the activation of the immune response via the IRF3/NF-KB pathway, TLR3 is emerging as a potential anti-tumor target in cancers, due to its ability to induce different death signals, depending on the cellular context." (PMID 37414800, 2023). "Targeting TLR3 could then have two complementary anti-tumor effects, directly by triggering death signaling pathways in tumor cells, and indirectly, by stimulating anti-tumor immunity through cytokine release." (PMID 37414800, 2023). "Thus, tumor-specific cytotoxic T lymphocytes can be generated by targeting TLR3 signaling in DCs." (PMID 36365103, 2022). "Importantly, cM362-140 triggers exclusively TLR3, provoking an anti-tumor response without causing a cytokine storm." (PMID 36672572, 2022). "TLR3-specific RNA agonist ARNAX could activate tumor-specific CTLs, and overcome anti-PD-1 resistance without cytokinemia when combined with anti-PD-L1 antibody and a tumor-associated antigen." (PMID 35413927, 2022). "However, after the metastatic process initiation, TLR3 activation enhances tumor migration." (PMID 36411434, 2022). "Interestingly, TLR3 activation resulted in MSCs secreting some factors with mostly tumor supportive immunosuppressive effect (such as IL1RA and IL10), while TLR4 stimulation leaded to MSCs producing inflammatory and proapoptotic factors (such as IL17, GM-CSF, and TRAIL)." (PMID 34736460, 2021). "Therefore, we hypothesised that TLR3 might regulate immune infiltration and tumour progression in KIRC via kinase MAPK1." (PMID 34531911, 2021). "Importantly, in an ovarian cancer model, in situ co-administration of CD40 and TLR3 agonists has induced the polarization of tumor-infiltrating DCs into an immune stimulatory phenotype that was able to produce type I IFN and IL-12 p70, resulting in tumor remission." (PMID 34262904, 2021). "TLR3 may contribute to tumor development and lead to cisplatin resistance in OC2 cells." (PMID 33986756, 2021). "In addition, TLR3 expression and activation were specific to tumor cells, which could also provide potential rationales for targeting TLR3 with more safe therapy." (PMID 33036630, 2020). "Furthermore, ablation of histone H3K4 demethylase LSD1 resulted in upregulation of ERVs and accumulation of dsRNAs that are recognized by MDA5 and TLR3 in cancer cells, which promotes anti-tumor T cell immunity and elicits significant responses to anti-PD-1 therapy in a mouse melanoma model." (PMID 33633744, 2020). "Furthermore, the complexity of the tumor microenvironment, together with the well-known heterogeneity of tumor cells, might also influence the outcome of TLR3 activation." (PMID 33147700, 2020). "Intraperitoneal injection of Poly(I:C) one day before irradiation of LLC-OVA tumor enhanced the tumor shrinkage and, by the use of TLR3- and TICAM-1-deficient mice, the authors demonstrated that the effect was dependent on the activation of TLR3-TICAM-1 pathway." (PMID 33147700, 2020). "Therefore, the authors suggest that the tumor suppressing effects of TLR3 may come from the induction of hepatocyte death and the attraction/activation of immune cells to the tumor microenvironment." (PMID 33613561, 2020).
tumor (continued). "Furthermore, tumor exoRNAs can activate lung epithelial cell TLR3 to recruit neutrophils due to the expression of chemokine receptors (CXCR1, CXCR2, CXCR4, andCCR2) being higher in tumor-bearing Tlr3−/− mice, consequently inducing lung premetastatic niche formation." (PMID 30849983, 2019). "Literature data on PCa have demonstrated tumour-suppressive functions of TLR3, a receptor for viral double-stranded RNA (dsRNA), and it has been shown that poly(I:C), a synthetic analog of dsRNA, exerts both a direct apoptotic effect on TLR3-expressing cancer cells and anticancer immune stimulation." (PMID 30112117, 2018). "Furthermore, injection of polyinosinic:polycytidylic acid (polyI:C) into Lewis lung carcinoma tumor–implanted mice to activate the TLR3/Toll–IL1 receptor domain–containing adaptor molecule 1 (TICAM-1) switches tumor-promoting macrophages into tumor suppressors." (PMID 28467800, 2017). "Hence, TLR3 ligand may bimodally act on TLR3 expressed in tumor cells and immune cells, leading to tumor regression." (PMID 29041928, 2017). "Shime and colleagues found in tumor-bearing mice that induction of the assembly of pro-inflammatory cytokines and subsequently acceleration of M1 macrophage polarization has been activated promptly by TLR3/Toll-IL-1 receptor domain-containing adaptor molecule 1 by Poly(I:C)." (PMID 29450136, 2017). "Thus, activation of TLR3 is a major factor in antiviral defense and tumor eradication." (PMID 28127569, 2017). "The observation that TLR3 is expressed in the plasma membrane of metastatic epithelial cells and that TLR3-dependent CXCL10 induction can occur in response to extracellular stimuli suggests that malignant TLR3-expressing IECs could potentially respond to TLR3 ligands in the tumor microenvironment." (PMID 28717003, 2017). "The importance of TLR in providing protection against tumour development could be extrapolated from the results demonstrating significantly higher basal expression levels of TLR3 and TLR7 in uninfected chicken cells isolated from resistant chicken lines compared to the susceptible lines." (PMID 27894330, 2016). "Indeed, TLR3 agonists-induced tumor cell death was reported in multiple cancer cell lines as well." (PMID 26287667, 2015). "TLR3_rs3775291 may also have clinical importance, since TLR3 agonists have been implemented as adjuvant therapy in clinical trials for different types of cancer and therapeutic response may depend on TLR3 status of the tumor tissue." (PMID 23576520, 2013). "In accordance with the third model, our group has previously demonstrated that activation of TLR3 in PCa cell lines induces the secretion of cytokines and chemokines that could recruit and activate immune cells in the tumour site consequently promoting their anti-cancer activity." (PMID 23551576, 2013). "Interestingly, TLR3 agonists can elicit the production of a range of chemokines by tumor cells." (PMID 23056170, 2012). "Our work shows that TLR3 is widely expressed in human and murine tumor cells lines from different origin though at different levels, suggesting that TLR3 activation may play important functions in tumor biology." (PMID 18199340, 2008). "Toll-like receptor 3 (TLR3) is a double-stranded RNA sensor that plays a dual and context-dependent role in epithelial cancers, promoting either regulated cell death (RCD) or tumor-supportive programs." (PMID 42278599, 2026). "Both in vitro and in vivo experiments revealed that IFN-β secretion driven by the TRIM3/TLR3 axis suppressed NSCLC cell proliferation and tumor growth." (PMID 41545343, 2026). "When combined with poly(I:C), an immunostimulatory TLR3 agonist, Flt3L-secreting CAR T-cells significantly suppressed tumor growth in both antigen-homogeneous and heterogeneous tumor models." (PMID 41019052, 2025).
tumor (continued). "Both poly-I:C and rintatolimod activate TLR3-mediated nuclear translocation of TRAF3 and IRF3, leading to type-1 interferon production and CXCL10 expression, which attract CD8+ T cells for anti-tumor immunity." (PMID 39949780, 2025). "In the tumor microenvironment (TME), PS-positive tumor EVs contribute to inhibition of TLR3-mediated IRF3 and IFN-β expression through binding with CD300a on DCs." (PMID 40507267, 2025). "When examining transcriptomic responses of MSC themselves following activation, TLR3 activation responses were dominated by interferon responses, consistent with prior reports of MSC and tumor cells activated with these agonists." (PMID 40861855, 2025). "Systemic administration of Flt3L, followed by a TLR3 agonist poly(I:C) or CD40 agonist, has been reported to successfully promote the expansion and activation of tumor-residing cDC1s and enhances tumor responses to anti-PD-L1 therapy." (PMID 41459487, 2025). "Among all adjuvants available for cancer vaccines, we selected the TL3 agonist Poly I:C because dendritic cell 1 (cDC1) expresses TLR3, and its activation results in the induction of cytotoxic CD8+ T cells, which are crucial for an anti-tumor response." (PMID 40573960, 2025). "CASP8 and PGAM5 were identified as potential biomarkers among these, while previous studies have shown that ZBP1, TLR3, and PYGL contribute to tumor progression in KIRC." (PMID 40969770, 2025). "For instance, in colon cancer (CRC), TLR3 and TLR4 can jointly express chemokines, increase the infiltration of tumor macrophages, and support malignant progression of the tumor." (PMID 40727252, 2025). "Tumor-derived extracellular vesicles carrying PS bind to CD300a on DCs, and suppress TLR3-mediated IFN-β production, leading to enhanced in vitro accumulation of tumor-infiltrating Tregs." (PMID 40507267, 2025). "We demonstrate here that TLR3 activation promotes stemness in HNSCC cells, as evidenced by larger tumor sphere formation, upregulation of stemness- and EMT-related genes, and elevated ALDH activity." (PMID 40647457, 2025). "Systemic administration of Flt3L, followed by a TLR3 agonist poly(I:C) or CD40 agonist, has been reported to induce the expansion and activation of tumor-residing cDC1s and enhances tumor responses to anti-PD-L1 therapy." (PMID 38926350, 2024). "For example, clinical trials combining TLR3 and TLR7/8 agonists with cancer vaccines have led to disease stabilization and tumor regression in some patients." (PMID 39451226, 2024). "The upregulation of TLR3 (3.79×) and CD36 (2.73×), two general tumor markers, and SERPINEB9 (11.37×), FNDC1 (7.58×), and TACR2 (8.84×), three factors of tumorigenesis, confirms the wider pathological significance of this bacterium." (PMID 38787238, 2024). "It is worth mentioning that previous studies have confirmed TLR3 activation promoted NK cell activation and cytotoxicity in vitro, thus, it will also be interesting to investigate whether poly(I:C) also exerts anti-tumor effects by activating the TLR3 receptor of NK cells." (PMID 38671318, 2024).